SOX10 (SRY-box transcription factor 10)
Diseases named in the same sentence as SOX10 in open-access papers (continued):
Sharing a sentence is not in itself a finding about the gene and the disease.
melanoma (continued). "Although we are unable to dissect the connection of CD271 and SOX10, yet our study provides a deeper insight in the CD271-dependent signaling network and reveals that this network comprises several genes known as drivers of melanoma progression and metastasis." (PMID 24799129, 2014). "The spontaneous transition of CD271+ sorted melanoma cells towards CD133+ in standard medium may also depend on the level of TGFβ-signaling and needs both low levels of CD271 and SOX10." (PMID 24799129, 2014). "Clearly, strong nuclear immunostaining of SOX10 was found in all melanoma cases, while the negative control treated identically with a normal mouse IgG antibody showing no staining, in agreement with previous report." (PMID 25301735, 2014). "Using mutagenesis, co-transfection experiments and chromatin immunoprecipitation, we showed that transcription factors involved in meloe promoter activity in melanomas were the melanocytic specific SOX9 and SOX10 proteins together with the activated P-CREB protein." (PMID 24086527, 2013). "Several studies regarding the role of Sox10 in melanoma indicate that Sox10 is expressed in most if not all primary and metastatic melanoma cells and drives the expression of nestin which is correlated with poor prognosis." (PMID 22363655, 2012). "While we noted that primary cilia were slightly more apparent in metastatic lymph node deposits as compared to primary melanomas, we did not encounter a metastatic deposit in which greater than 10% of the Sox10 positive cells were ciliated." (PMID 22096570, 2011). "Two of the four melanoma cell lines did not reveal increased SOX10 expression, although they retained increased MITF expression, upon inhibition of ATF2 (Lu1205, WM35)." (PMID 21203491, 2010). "Over-expression of JunB, but not Jun D, effectively inhibited Sox10 expression in both the melanoma and melanocytes cells." (PMID 21203491, 2010). "Importantly, ATF2-dependent negative regulation of Sox10 and consequently of MITF seen in melanocytes, but only in about 50% of the 18 melanoma cell lines studied here." (PMID 21203491, 2010). "Surprisingly, ATF2 control of melanoma development was mediated, in part, through its negative regulation of SOX10 and consequently of MITF transcription." (PMID 21203491, 2010). "We therefore assessed whether SOX10, which positively regulates MITF and whose transcription markedly increases in melanocytes and melanoma cells in which ATF2 expression is inhibited, may mediate ATF2 effect on MITF transcription." (PMID 21203491, 2010). "Correspondingly, JunB, which is required for ATF2-dependent inhibition of Sox10 transcription, is no longer found on the promoter of SOX10 in melanoma cells (i.e. 501Mel) that exhibit positive regulation by ATF2." (PMID 21203491, 2010). "SOX10 is important for melanin production and the SOX10 promoter methylation (>80%) in both pigmented and white hair, but not in melanoma cell lines, implies lack of expression." (PMID 16457718, 2006). "Specifically, SOX10 has demonstrated greater expression stability compared to S100 in melanoma diagnostics, while Melan-A may be negative in amelanotic variants, highlighting the need for panel-based interpretation rather than reliance on individual markers." (PMID 41002705, 2025). "Histological analysis using SOX10 staining further confirmed the absence of melanoma cells." (PMID 41432764, 2025). "Histologically, tumors from Plp1::CreERT2; BrafCA/+; Ptenlox/+ animals were indistinguishable from their Ptenlox/lox counterparts, including the extensive infiltration of non-traced (tdTomato− and/or Sox10−) stromal cells, which was markedly higher compared to melanoma samples." (PMID 41063628, 2025). "EMPD does not express SOX10, whereas melanoma typically does." (PMID 40026956, 2025).
melanoma (continued). "Mechanistically, SOX10 functions as a critical activator of both MAPK and PI3K pathways, and intriguingly, its reactivation can paradoxically drive resistance through promoting melanoma cell dedifferentiation, highlighting the context‐dependent role of this transcription factor." (PMID 40458894, 2025). "Melanomas with a high proliferative index show high MITF expression; as SOX10 regulates the MITF pathway, it may suggest that invasion in oral melanoma occurs due to low MITF levels and high ZEB1 expression or through direct activation of the activity inhibitory melanoma (MIA) to invasion." (PMID 41012776, 2025). "From an immunohistochemical point of view, S-100 protein, HMB-45, Melan-A, SOX-10, and MiTF are usually positive (melanocytic line differentiation features) and recently also it was demonstrated the potential utility of negativity for PRAME in the differential diagnosis with melanoma." (PMID 40004764, 2025). "Our analyses were performed in only two melanoma cell lines, which may not capture the full heterogeneity of melanoma subtypes with distinct MITF- or SOX10-dependent phenotypic states." (PMID 41465475, 2025). "The tumor‐suppressive miR‐107, frequently downregulated in melanoma, exerts its anti‐proliferative and anti‐invasive effects by targeting POU3F2,113 a transcription factor that interacts with both SOX10 and MITF in melanocytes, thus indirectly affecting the SOX10‐MITF regulatory network." (PMID 40458894, 2025). "On the other hand, metastatic or primary squamous cell carcinomas typically show negative staining for CK7, CK20, and SOX10 (positive in melanoma), and positive staining for p63 and CK5/6, although clinical correlation is necessary to distinguish between metastases and primary squamous carcinomas." (PMID 39125514, 2024). "SOX10 expression was proposed to be suppressed by therapy-related factors, i.e., radiation treatment in a glioblastoma mouse model, TGF-β-mediated stress signaling activated by irradiation, hypoxia, or TMZ in human glioma cells, and BRAF inhibition in melanoma patients." (PMID 39285246, 2024). "To investigate this, we classified melanoma cell lines as either EP300/SOX10 co-amplified (>2 copies of both EP300/SOX10) or not co-amplified, treated them with the potent and specific p300 KAT inhibitor A-485, and probed for SOX10 and downstream SOX10 target genes, such as MITF and DCT." (PMID 38994683, 2024). "Other immunostains, such as SOX10, melanoma, and H3.3G34W, were all negative." (PMID 38643211, 2024). "Strikingly, we find that p300 KAT activity is essential for SOX10 protein stability and that inhibition of p300 KAT with the small-molecule inhibitor A-485 inhibits the expression of SOX10 target genes and SOX10-dependent melanoma growth in SOX10+ melanoma cell lines, regardless of the MITF status." (PMID 38994683, 2024). "Moreover, PRAME usually stains melanoma cells and is negative in non-tumoral melanocytes, in comparison with Melan-A and SOX10 that stain all melanocytes." (PMID 36980327, 2023). "However, caution is advised, and a more sensitive stain for melanoma should be considered due to the non-exclusive expression of SOX10." (PMID 38132479, 2023). "We therefore propose that identifying expression levels of MITF/SOX10, AXL/EGFR/ERBB3 prior to initiation of treatment may contribute to predicting treatment response to MAPK inhibitors and perhaps advice on drug combination strategies in melanoma." (PMID 36251678, 2023). "As expected, our drug-resistant melanoma cells and SOX10 knockout cells were resistant to MG1 but not to vaccinia virus infection, suggesting that this phenotype is conserved among RNA viruses and that these cells become “primed” to RNA virus infection upon acquiring a drug-resistant state." (PMID 38201278, 2023).
melanoma (continued). "Melanocyte and NC programs are particularly active in melanoma cells, with increased sox10 and mitfa expression, respectively, seen in the RNA-seq data, and this appears consistent with enrichment of SOX9/10 (SOXE family) and MITF (E/M-boxes) binding sites in more accessible regions in melanoma." (PMID 34791221, 2022). "However, melanoma cells from the SOX10– cell lines (IGR-39 and LOX) formed aggregates whereas the melanoma cells from the SOX10+ cell lines (MM383 and WM278) grew as single-cell suspensions, indicating an added property to mimic the structural character of microtumors." (PMID 36040798, 2022). "In line with this, and alike others, we observed that melanoma cells can undergo further dedifferentiation, losing neural crest features that are prominent in the intermediate state, such as expression of nerve growth factor receptor (NGFR), Erb-B2 receptor tyrosine kinase 3 (ERBB3), and SOX10." (PMID 36434616, 2022). "In addition, immunofluorescence staining in melanoma tissue arrays showed that expression levels of SOX10, DEPDC1B and CDC16 were high in nevi which do not metastasize but SCUBE3 was barely detectable." (PMID 35088579, 2022). "In order to track the melanoma cells using EGFP instead of melanin, we bred the sox10:EGFP fluorescent zebrafish line into our nf1/pten-mutant line to aid in visualization of the transplanted melanoma cells, as they expressed high levels of the neural crest progenitor marker sox10." (PMID 34331013, 2021). "If SOX10/SOX11 double positivity might serve as an indicator of lymphatic invasion, triple SOX11/SOX10/MITF gene interaction might induce genesis of a subtype of MMs which do not express positivity for the conventional pan-melanoma cocktail." (PMID 33801642, 2021). "SOX10 is specifically upregulated in melanoma tissues compared with control tissues according to the Gene Expression Profiling Interactive Analysis (GEPIA) database; in addition, it promotes both melanoma initiation and progression and serves as a biomarker for the detection of UM." (PMID 34249897, 2021). "We further investigated the possibility of an alternative diagnosis including either a rhabdomyosarcoma or a melanoma, both of which have recurrent NRAS mutations, but the tissue was negative for all markers specific to these tumor types (SOX10, S100, myf4, and desmin)." (PMID 32191822, 2021). "However, there was no sufficient difference in SOX10 expression between primary and metastasis melanoma tissue." (PMID 34526609, 2021). "Since then, there has been a case report of SOX10 negative desmoplastic melanoma." (PMID 34449584, 2021). "Altogether, our results demonstrate that SOX10 or high level of SOX9 expression could regulate focal adhesion dynamics and Rho GTPase signaling, partly through modulation of NEDD9 activity to promote mesenchymal migration of melanoma." (PMID 30642390, 2019). "Conversely, opposite phenomenon was observed when SOX9 expression was further elevated to a range of high SOX9 expression levels in metastatic melanoma specimens, and that high levels of SOX9 can restore melanoma progression in the absence of SOX10 both in vitro and in vivo." (PMID 30642390, 2019). "To further determine whether SOX10 and/or SOX9 can regulate NEDD9 expression through transactivating its promoter, we performed luciferase reporter assay driven by the NEDD9 promoter (~ 1 kb) in both A375M and WM266–4 melanoma cell lines." (PMID 30642390, 2019). "Whether SOX9 and/or SOX10 exhibit a similar regulatory relationship with NEDD9 in melanoma has not yet been examined." (PMID 30642390, 2019). "In addition, the ERK1/2/SOX10/FOXD3 axis appears to be specific to mutant BRAF melanoma cells since N-RAS mutant melanoma cells have no detectable level of basal or induced FOXD3 expression." (PMID 29295999, 2018). "We analyzed whether there is a regulatory relationship between SOX10 and FOXD3 in melanoma cells." (PMID 29295999, 2018).
melanoma (continued). "To investigate the role of SOX10, MITF, and FOXD3 and the reported effects due to BRAF status in ERBB3 regulation, we depleted the three former genes individually and in combination for MITF/FOXD3 by the use of siRNA in three melanoma cell lines: WM983B, MeWo and WM115." (PMID 27391157, 2016). "However, while SOX10 and MYC control a wide variety of cellular processes in melanoma cells, they have not been directly linked to endolysosomal trafficking." (PMID 26008978, 2015). "To confirm the downregulation of SOX10 upon SOX9 overexpression observed in microarray analysis also on the protein level, we performed Western blot analysis and observed a pronounced downregulation of SOX10 protein upon SOX9 overexpression in human melanoma cell lines." (PMID 25629959, 2015). "Thus, SOX10 and SOX9 are functionally antagonistic regulators of melanoma development." (PMID 25629959, 2015). "First, Sox10 appears to be broadly expressed in both metastatic and non-metastatic melanomas." (PMID 22363655, 2012). "In two out of the 12 melanoma lines ATF2 affected SOX10 but not MITF transcription." (PMID 21203491, 2010). "In order to determine whether JunB lost its ability to elicit negative regulation of SOX10 and MITF in melanoma cells where ATF2 no longer inhibited SOX10 or MITF expression, we transfected those cell lines with TAM67 and JunB alone and in combination." (PMID 21203491, 2010). "Immunohistochemical staining was negative for pancytokeratin, showing diffuse positivity for SOX10 (a transcription factor and sensitive, specific marker for melanoma) and patchy/weak staining for S100 (low-molecular mass proteins and immunohistochemical markers of malignant melanoma)." (PMID 37983006, 2025). "Finally, desmoplastic melanomas represent particular entities as they may appear deceivingly bland and usually lack expression of melanocytic markers such as HMB45, MelanA, tyrosinase, and PRAME but generally express S100 and SOX10." (PMID 37373134, 2023). "Notably, compared to the main effect of immune score only, the multivariable analysis presented an additive interaction of SOX10 with an immune score to predict OS in patients with early-stage (likelihood ratio [LR] test, p = 0.005), but not late-stage melanoma (LR test, p = 0.554)." (PMID 35058553, 2022). "Moreover, GAPDHS was identified as one of the top differentially expressed genes in human melanoma cells with NGLY1 knockdown, so it is also important to determine whether SOX10 cooperates with NGLY1 or other transcriptional regulators to promote melanomagenesis." (PMID 34249897, 2021). "Notably, our results suggest connections between SOX10 and BRAF in the etiology of skin cancer and modulating their shared DDPs via chemotherapeutics might open a new avenue to rescue resistance to BRAF/MEK inhibitors in melanoma patients." (PMID 33842927, 2021). "Importantly, the upregulated levels of SOX9 expression in SOX10 KD A375 (1.5 to 2.6 fold) and WM266–4 (1.5 to 3.4 fold) are clinical relevant as they fall within the range of SOX9 expression levels detected in some specimens of primary melanoma (1.3 to 3.7 fold)." (PMID 30642390, 2019). "Interestingly, both MITF and the lncRNA SAMMSON reside within this amplicon, suggesting that a proportion of melanoma patients alter oxidative metabolism through two unique independent mechanisms, the SAMMSON-p32 axis and the MITF-PGC1α axis, both of which are regulated by SOX10." (PMID 31416288, 2019). "Interestingly, Agnarsdottir and co-workers showed that inhibition of Sox10 expression with siRNA led to down-regulation of migration in the case of WM115 melanoma cells but not in the case of WM793 cells suggesting that the role of Sox10 is not equivalent in all melanoma cells." (PMID 22363655, 2012). "Conversely, Myc-DDK-SOX10 (ΔUTR) enhances this effect, thereby indicating that the involvement of HK2 on the migration properties of melanoma cells is independent of the SOX10 UTR." (PMID 40956859, 2025).
melanoma (continued). "MGNET typically shows positivity for S100 and SOX10 while being negative for melanocytic markers like HMB-45, Melan-A, and MiTF, which are usually present in melanoma and CCS." (PMID 40429661, 2025). "Similarly, in the MIR155‐SOX10‐MITF FFL, miR‐155 may prolong the time required for producing the protein products of MITF or stabilize MITF expression against sudden activation or deactivation of SOX10 transcription to ensure desired melanoma cell phenotypic transitions." (PMID 40458894, 2025). "Melanoma often exhibits marked nuclear pleomorphism and is positive for Melan A, HMB45, and Sox10—all negative in our case." (PMID 41409361, 2025). "Overall, these data show that despite no overt change in TAZ/TEAD expression, SOX10-low, drug-tolerant cells exhibit up-regulation of YAP1/TAZ-TEAD signaling in melanoma, likely through multiple mechanisms including chromatin remodeling and c-Jun upregulation." (PMID 41193428, 2025). "Similarly to SOX2 and unlike the literature, which demonstrates the presence of SOX10 in the cell nucleus, our studies indicated the existence of this protein mainly in the cytoplasm, together with the formation of perinuclear clusters in the studied melanomas." (PMID 41012776, 2025). "Immunostains were strongly positive for SOX10 and PRAME (preferentially expressed antigen of melanoma); while negative for BRAF, VE1, NRAS, Q61L, and DOG1." (PMID 38933829, 2024). "Conventional squamous and melanoma markers such as CK5/6, p40, S100, and SOX10 are consistently negative." (PMID 38658519, 2024). "While S100 protein and SOX10 are typically positive in both MCNH and melanoma, the absence of other melanocytic markers, such as Melan-A and HMB-45, can support a diagnosis of MCNH." (PMID 39421096, 2024). "In MITFlow/DCTlow A375, Sk-Mel-24, and WM793 melanoma cells without EP300/SOX10 co-amplification, SOX10 protein expression was also found to be downregulated following treatment with A-485." (PMID 38994683, 2024). "Histopathology showed the presence of melanoma cells (HMB45+, SOX10+, desmin-, panCK-) with a negative immunohistochemistry for V600E BRAF mutation and positive for c-Kit." (PMID 39605889, 2024). "Western blot analyzed the expression of SOX10, Notch1, and HES1 in melanoma cell treated with or without miR-222-3p inhibitor." (PMID 35585935, 2022). "Together, our data revealed significant interaction and an additive effect of the prognostic value of SOX10, confirmed by another melanoma marker MLANA, with an immune score in early- but not late-stage melanoma." (PMID 35058553, 2022). "We have previously demonstrated that melanoma persister cells in the MRD site do not express Mitfa protein (called MITF independent), but maintain a neural crest identity and express Sox10." (PMID 35929478, 2022). "The independent prognostic value was proved for the conventional pan-melanoma cocktail (triple positivity for HMB-45, melan-A, and tyrosinase) and, independently for HMB-45 and tyrosinase, but not for melan-A, SOX10, or SOX11." (PMID 33801642, 2021). "Importantly, this striking effect on SOX10 protein levels was present in all melanoma cultures, irrespective of whether they harbor activating BRAF p.V600E, NRAS p.Q61K, or both mutations, and irrespective of whether they are sensitive to MAPK inhibition or resistant." (PMID 32238882, 2020). "Without analyzing single-mismatch alignments of guides targeting SOX9, one would have erroneously concluded that most of the melanoma cell lines in the Achilles dataset have a SOX9, rather than a SOX10, dependency." (PMID 30683138, 2019). "Overall, there results confirm specificity of the SOX9 and SOX10 siRNAs, and that SOX10 knockdown, unlike SOX9 knockdown, reduces cell viability in melanoma cell lines." (PMID 30683138, 2019). "Unlike SOX10, SOX9 is not required for normal melanocyte stem cell function, the formation of hyperplastic lesions, and melanoma initiation." (PMID 25629959, 2015).